EPO (erythropoietin)
Diseases named in the same sentence as EPO in open-access papers (continued):
Sharing a sentence is not in itself a finding about the gene and the disease.
iron metabolism disorder (19 papers, 2015 to 2025). "The mechanism of renal anemia is complex, involving shortened red blood cell lifespan, deficiency and dysfunction of erythropoietin (EPO), iron metabolism disorders, and other factors (Podkowińska and Formanowicz, 2020)." (PMID 41311841, 2025). "It promotes the production of endogenous EPO and corrects iron metabolism disorders, and is effective in the treatment of renal anemia avoiding plasma EPO concentration peaks compared to ESAs treatment." (PMID 34657570, 2021). "In addition, proinflammatory cytokines can lead to iron metabolism disorder and reduce the production of erythropoietin and the response of bone marrow to erythropoietin, resulting in impaired hematopoietic function and increased RDW levels." (PMID 35252370, 2022). "However, an increasing number of patients also present clinically with EPO hyporesponse, which may be related to factors such as iron metabolism disorder and EPO receptor dysfunction." (PMID 36517799, 2022). "There are also a number of hypotheses about the causes of increased RDW, including the possible origin of bone marrow suppression, and that chronic inflammation leads to an iron metabolism disorder that reduces the production of erythropoietin, which may impair hematopoietic function." (PMID 34524510, 2022).
retinopathy (19 papers, 2007 to 2025). "Of the molecules found in the fetal vitreous, lutein can be useful in the treatment of oxygen-induced retinopathy, and EPO against various eye diseases." (PMID 41008946, 2025). "Our results suggest that the INas delivery of EPO is effective to alleviate the retinopathy of the MNU administered mice." (PMID 30744451, 2019). "For instance, in a mouse model of retinopathy, early EPO administration provided protection to hypoxia-induced retinal neuron apoptosis, while late administration enhanced pathological revascularization." (PMID 22567318, 2012). "Similarly, intravitreous injection of EPO siRNA inhibits endogenous expression of EPO in the retina, followed by the suppression of destructive vessel proliferation during the neovascular phase of retinopathy." (PMID 28703764, 2017). "The aim of this study was to examine the effect of erythropoietin (EPO) on retinopathy in RCS rats." (PMID 25119659, 2014). "All patients completing this study will be eligible for entry into a 2-year, open-label extension to enable monitoring of emergent adverse events, anti-erythropoietin antibody responses, maintenance of efficacy and changes in retinopathy status among the diabetic subpopulation." (PMID 17999759, 2007). "The present study is designed to deliver the erythropoietin (EPO) into the N-methyl-N-nitrosourea (MNU) induced mice, a pharmacological retinopathy model via intranasal or intravenous route." (PMID 30744451, 2019). "On the other hand, late EPO treatment does not have any protective effect on retinal vasculature during the neovascularization phase of retinopathy, but can worsen pathological proliferation." (PMID 28703764, 2017). "Consistent with a role in DR, EPO shows overexpression in the retina of diabetic patients without clinically detectable retinopathy compared to non-diabetic controls." (PMID 25487307, 2015). "Association between elevated EPO in the vitreous and proliferative retinopathy was observed in adult diabetic patients exhibiting increased levels of VEGF and EPO in the vitreous fluid compared with nondiabetic patients with ocular disease." (PMID 22567318, 2012). "There is no direct clinical evidence that systemic EPO can promote accelerative retinopathy in people with diabetic renal failure." (PMID 20686695, 2010). "The patients were only assessed up to 18 weeks after the first injection and there was no mention of the EPO treatment promoting accelerative retinopathy but the patients were only assessed for 18 weeks." (PMID 20686695, 2010). "Others demonstrated the neuroprotective effect of endogenous EPO in oxygen-induced retinopathy, but could not increase this effect by adding exogenous EPO." (PMID 25013951, 2014). "Another in vivo study confirmed that compared to IVB alone with intravitreal IVB, IVB combined with EPO did not significantly improve visual acuity and reduce retinal thickness in DME patients, nor did any retinopathy progression or neovascularization." (PMID 34621759, 2021).
hematologic diseases (16 papers, 2008 to 2025). "Our findings that PKA is an effector of EPO/JAK2 signaling implicate PKA activity not only in the pathogenesis of EPP but also a spectrum of hematologic diseases." (PMID 28553927, 2017).
cardiac disease (12 papers, 2014 to 2024). "Emerging roles in cardiac disease therapies have been demonstrated for hematopoietic cytokines like GCSF, granulocyte macrophage colony-stimulating factor (GM-CSF), SCF, Flt-3 ligand, and erythropoietin (EPO)." (PMID 25054145, 2014). "In their study, users had a higher prevalence of heart diseases, CCI scores, the use of statins or aspirin, and erythropoietin doses than non-users." (PMID 38551953, 2024).
psychiatric disorder (11 papers, 2018 to 2026). A disorder characterized by behavioral and/or psychological abnormalities, often accompanied by physical symptoms. "Consistent with studies in other psychiatric disorders, our study provides evidence supporting the potential use of EPO levels as a diagnostic biomarker in OCD." (PMID 38995319, 2024). "Due to EPO’s activity on the CNS, EPO levels or the efficacy of EPO treatment has been the subject of research, especially in psychiatric disorders." (PMID 38995319, 2024). "Erythropoietin (EPO) is a neurotrophic factor known to improve cognitive function in preclinical and clinical studies of neurodegenerative and psychiatric disorders." (PMID 37511274, 2023). "Despite the promising results in psychiatric disorders, it is important to note that EPO has potent erythropoietic activity." (PMID 33921564, 2021). "Erythropoietin (Epo) has shown promising procognitive effects in psychiatric disorders, providing support for a neurotrophic drug development approach." (PMID 34552490, 2021). "This redefines EPO as a precision tool for neurorestoration, a potential now being pursued with engineered, non-erythropoietic variants of EPO in clinical trials for neurological and psychiatric disorders." (PMID 42196309, 2026). "Promising results from clinical testing of erythropoietin (EPO) in multiple psychiatric diseases strengthen the hypothesis that it produces behavioral effects via central mechanisms associated with the neurobiology of cognition." (PMID 34552490, 2021). "Clinical studies of the cognitive effects of EPO in psychiatric diseases." (PMID 34552490, 2021). "In recent years, erythropoietin (EPO) has emerged as a useful neuroprotective and neurotrophic molecule that produces antidepressant and cognitive-enhancing effects in psychiatric disorders." (PMID 33921564, 2021). "EPO and non-erythropoietic derivatives have also shown potential pro-cognitive effects in psychiatric disorders." (PMID 38993198, 2024).
brain diseases (9 papers, 2009 to 2025). "Explaining the multifaceted brain EPO system, however, will be pivotal to understand adaptive brain mechanisms and develop novel treatment strategies for brain diseases, exploiting both, rhEPO and hypoxia-induced brain EPO." (PMID 35414656, 2022). "The preclinical data in support of the use of EPO in brain disease have already been translated to first clinical pilot studies with encouraging results with the use of EPO as a neuroprotective agent." (PMID 20142991, 2009). "The preclinical data in support of the use of EPO in human brain disease have explosively increased since the first discovery of its neuroprotective action." (PMID 20142991, 2009). "Re-engineering of EPO as the HIRMAb-EPO fusion protein fulfills both criteria for development of EPO as a biologic for brain disease: (a) penetration of the BBB, and (b) large reduction in the plasma AUC of EPO, which causes a proportionate reduction in erythropoietic action of the EPO." (PMID 38035276, 2023). "Erythropoietin (EPO) is a neurotrophic factor that could be developed as a drug for brain disorders." (PMID 23840214, 2013). "EPO is a potent growth factor, not a miracle drug, and it is no causal treatment or cure of brain diseases but it may improve their outcome." (PMID 32546125, 2020). "Recently, erythropoietin (EPO), stem cell therapy, transcranial magnetic stimulation (TMS), and transcranial direct current stimulation (tDCS) have been proposed as potential therapeutics for brain diseases." (PMID 38317779, 2024).
immune dysfunction (8 papers, 2009 to 2025). "Pathogenesis of PRCA is heterogeneous where it involves immune dysfunction with antibodies directed against erythroid precursor cells or erythropoietin, or due to T cell-mediated suppression of erythropoiesis." (PMID 34872595, 2021). "Future studies should investigate whether targeting the EPO pathway or modulating the immune microenvironment could ameliorate splenic pathology and immune dysfunction in these patients." (PMID 40191193, 2025).
kidney (8 papers, 2014 to 2025). "In the event of kidney injury, EPO-producing perivascular cells lose their capacity to produce EPO by transdifferentiating into myofibroblasts." (PMID 38630367, 2024). "EPO was found to ameliorate kidney injuries by reducing macrophages recruitment and promoting phenotype switch toward M2 macrophages in vivo." (PMID 28383559, 2017). "Another study showed the neuroprotective effect of IGF1 and erythropoietin combination treatment via intranasal delivery in the middle cerebral artery occlusion model." (PMID 24959881, 2014). "Since we proved that a local supplement of EPO was beneficial for injured kidneys, we proceeded to design a novel system that could release EPO spontaneously in response to the kidney injury." (PMID 41179707, 2025).
bacterial infection (7 papers, 2012 to 2025). "CpG-ODN administration significantly increased EPO levels at day 4 after stimulation, similar to what was observed after bacterial infection." (PMID 32849551, 2020). "However, the role of EPO in bacterial infection resolution remains to be explored." (PMID 33927725, 2021). "In mammals suffering from systemic bacterial infection and not receiving anti-microbial therapy, EPO appears to be detrimental by blocking protective pro-inflammatory immune responses." (PMID 22094132, 2012).
infectious disease (6 papers, 2012 to 2025). A disorder directly resulting from the presence and activity of a microbial, viral, or parasitic agent in humans. "Recent studies have characterized EPO as a potent anti-inflammatory cytokine in chronic inflammatory disorders and infectious diseases." (PMID 22094132, 2012). "EPO has been therapeutically used in infectious diseases to treat pathogen-induced hemolytic anemia." (PMID 22094132, 2012). "Experimental data on the potential role of the EPO-EPOR system for infectious diseases have emerged recently." (PMID 22094132, 2012). "CAP is a typical infectious disease, during which Inflammation stimulates the release of inflammatory factors, damages the activity of erythropoietin, prevents the maturation of RBCs, leads to the production of ineffective RBCs, increases the heterogeneity of RBC size, and RDW value." (PMID 36650467, 2023). "Thus, the relative importance of EPO for defense against bacteria depends on pathogen biology and care must be taken when targeting EPO as a treatment for specific infectious diseases." (PMID 33927725, 2021). "It is currently unknown however, whether the interactions of HIF-1α and NF-κB pathways also affect the EPO-EPOR system in infectious diseases." (PMID 22094132, 2012). "Whether or not treatment with EPO also affects immunoglobulin production in active infectious diseases has not been studied to date." (PMID 22094132, 2012). "The first is to compare the sensitivity of the EPO intron-spanning PCR to a target that has no competition with human genomic DNA, and the second is to demonstrate the applicability to using the ITC approach for infectious disease diagnosis and treatment monitoring." (PMID 22570718, 2012).
inflammation (4 papers, 2012 to 2025). Aberrant reaction of the microcirculation characterized by movement of fluid and leukocytes from the blood into extravascular tissues. "Our previous study has successfully established EPO-modified BM-MSCs (EPO-BM-MSCs), demonstrating the ability of EPO-BM-MSCs to relieve asthmatic airway inflammation and remodeling." (PMID 41023810, 2025). "This intrauterine increase in EPO may be neuroprotective since EPO application can lessen retinal injury during intrauterine inflammation." (PMID 23109841, 2012).
neurodevelopmental disorder (4 papers, 2021 to 2025). A behavioral and cognitive disorder with onset during the developmental period that involves impaired or aberrant development of intellectual, motor, or social functions. "The secondary aim was to assess the association of us-EPO with minor neurodevelopmental disorders in early childhood and infant mortality by the age of 1 year." (PMID 34465877, 2022). "The primary objective was to determine whether early EPO administration could impact the short-term neurodevelopmental outcomes and provide safety in neonates at risk for neurodevelopmental disorders." (PMID 38804373, 2024). "The purpose of this study is to examine whether erythropoietin reduces the risk of death and improve neurodevelopmental disorders in infants with HIE." (PMID 34128891, 2021). "Other studies investigating the therapeutic potential of erythropoietin have demonstrated its ability to rescue three-chamber social approach behavior in rodent models of other neurodevelopmental disorders, including prenatal brain injury." (PMID 40137869, 2025). "Our hypothesis was that not only severe neurodevelopmental diseases but also minor neurodevelopmental disorders and mortality occur more often in children with high us-EPO than children with average us-EPO." (PMID 34465877, 2022).
Respiratory disorders (4 papers, 2022 to 2024). "Respiratory disorders can trigger an increase in erythropoietin production, which increases the number of erythrocytes and results in elevated RBC, HCT, HBG values." (PMID 35498756, 2022).
vasculopathy (3 papers, 2014 to 2021). "We describe here the protective effect of systemic EPO treatment on vasculopathy that develops as photoreceptors degenerate in RCS rats." (PMID 25119659, 2014). "CM has been termed by some as a vasculopathy, and studying the effects of EPO in mice without cerebral, endothelial EPO receptors would be highly relevant for assessing the contributions from endothelium to CM pathogenesis." (PMID 24995009, 2014).
central nervous system diseases (2 papers, 2017 to 2025). "Several prior reviews have examined the anti-apoptotic role of erythropoietin (EPO) in central nervous system diseases." (PMID 39744428, 2025).
endocrine disorders (2 papers, 2013 to 2025). "Uncollected information on erythrocytosis risk factors—such as familial history, history of renal transplantation, endocrine disorders, uterine myoma, and EPO-producing tumors—may have influenced the study results." (PMID 40640769, 2025).
head and neck tumors (2 papers, 2003 to 2023). "In patients with head and neck tumours receiving erythropoietin, an improved outcome of treatment has also been suggested." (PMID 14647149, 2003).
heart (2 papers, 2012 to 2018). "Other studies reported that EPC mobilization seems dependent on EPO dosing and myocardial restoration is probably associated with both adequate EPC mobilization and significant SDF-1 induction in the ischemic heart." (PMID 29752300, 2018).
connective tissue disorder (1 paper, 2021). A disease involving the connective tissue. "Study variables included a previous history of skin allergy (30.4%), use of calamine lotion (37.7%), topical steroids (10.4%), erythropoietin (60.0%), connective tissue disorder (3.7%), thrice-weekly dialysis (51.9%) and twice-weekly dialysis frequency (48.1%)." (PMID 34646616, 2021).
digestive diseases (1 paper, 2018). "Statistically significant differences were observed between the groups for all variables, except for gender, type of birth, presence of IVH, use of erythropoietin, maternal use of antenatal corticosteroids, and digestive diseases." (PMID 29881640, 2018).
genetic disorder (1 paper, 2024). "EPO therapy in SCA is a promising approach aimed at addressing the chronic anaemia that underlies this complex genetic disorder." (PMID 38463100, 2024). "As research in the field of SCA continues to evolve, EPO therapy represents a promising avenue toward extending the lifespan and improving the quality of life for those affected by this complex genetic disorder." (PMID 38463100, 2024). "In conclusion, the exploration of EPO therapy as a means to enhance life expectancy in individuals with SCA represents a significant step forward in the management of this complex genetic disorder." (PMID 38463100, 2024).
EPO also shares sentences with these, for which no sentence is quoted: acute myocardial infarction (14 papers); multiple myeloma (12); monoclonal gammopathy (11); pure red-cell aplasia (11); rheumatoid arthritis (8); Hypercalcemia (6); hypersplenism (6); hypogonadism (6); pheochromocytoma (6); Asphyxia and (5); Dialysis (5); Hyperbilirubinemia (5); hyperlipidemia (5); venous thromboembolism (5); vitamin deficiency (5); cardiac hypertrophy (4); cerebellar hemangioblastoma (4); eosinophilia (4); gestational diabetes (4); Myelodysplasia (4); myopathy (4); primary open angle glaucoma (4); Thyroid (4); vascular dementia (4); Anorexia (3); artery stenosis (3); cardiopulmonary disease (3); chronic myeloid leukemia (3); essential thrombocythemia (3); glomerular diseases (3).
A further 226 diseases each share a sentence with EPO in 3 papers or fewer.